NNMT (nicotinamide N-methyltransferase)
Diseases named in the same sentence as NNMT in open-access papers (continued):
Sharing a sentence is not in itself a finding about the gene and the disease.
renal fibrosis (continued). "Therefore, in the renal fibrosis model, renal NNMT expression was elevated, with a concomitant decrease in the upstream metabolites of NNMT and an increase in the downstream metabolites of NNMT." (PMID 35430611, 2022). "Therefore, this study demonstrated that NNMT is increased upon renal injury and exacerbates renal fibrosis through NAD + and methionine metabolism." (PMID 35430611, 2022). "Therefore, studies on the NNMT-KO and NNMT-Tg mice demonstrated that NNMT promotes renal fibrosis in vivo." (PMID 35430611, 2022). "Therefore, increased NNMT expression in the kidney and the associated changes in NAD + metabolism most likely contribute to the progression of renal fibrosis." (PMID 35430611, 2022). "Conversely, inhibition of NNMT may prevent the progression of renal fibrosis." (PMID 37953778, 2023). "Consequently, reducing renal inflammation at an earlier stage in NNMT-KO mice could ameliorate renal fibrosis after UUO induction." (PMID 35430611, 2022). "Overexpression of NNMT reduces NAD+ synthesis by depleting NAM, and it also decreases methylation activity of pro-fibrotic genes involved in renal fibrosis by depleting the methyl group of S-adenosylmethionine." (PMID 37953778, 2023). "However, the precise biological roles of NNMT in renal fibrosis remain unclear." (PMID 37953778, 2023). "Nicotinamide N-methyltransferase (NNMT) has been found to increase in kidneys with TIF, but its role in renal fibrosis is unclear." (PMID 37953778, 2023). "In conclusion, increased renal NNMT expression induces NAD + and methionine metabolism perturbation and contributes to renal fibrosis." (PMID 35430611, 2022). "Increased NNMT expression induces NAD + and methionine metabolism disturbance, thereby aggravating renal fibrosis through the regulation of DNA methylation of fibrotic genes and acetylation of NF-κB in the mouse model, and NNMT elevation may also be associated with renal fibrosis in human CKD." (PMID 35430611, 2022). "Since NNMT and NAD + metabolites were important in renal fibrosis in the mouse model, we decided to determine the significance of NAD + metabolism in patients with CKD." (PMID 35430611, 2022). "However, NNMT expression was significantly increased in the kidneys of UUO mice, with its expression and renal fibrosis positively correlating with the duration of obstruction." (PMID 37953778, 2023). "In other words, the present UUO model did not suggest that NNMT-KO improved oxidative stress, and the NADP/NADPH results also indicated that oxidative stress was unlikely to be the mechanism for the aggravation of renal fibrosis in NNMT-KO." (PMID 35430611, 2022). "Although NNMT is expressed abundantly in the kidney, its role in CKD and renal fibrosis remains unclear." (PMID 35430611, 2022).
oral cancer (7 papers, 2013 to 2026). "It has been demonstrated that the upregulation of NNMT is closely associated with oral cancer." (PMID 40427517, 2025). "In order to explore the involvement of NNMT in oral cancer cell metabolism, we analyzed NNMT expression in seven human oral cancer cell lines and the effect of enzyme knockdown on cell growth in vitro and in vivo." (PMID 23990942, 2013). "In this report, 7 human oral cancer cell lines were examined for NNMT expression by Real-Time PCR, Western blot and HPLC-based catalytic assay." (PMID 23990942, 2013). "Our results show that the downregulation of NNMT expression in human oral carcinoma cells significantly inhibits cell growth in vitro and tumorigenicity in vivo." (PMID 23990942, 2013). "In a recent study, a marked increase in enzyme activity in oral cancer and an up-regulation of salivary NNMT have been shown." (PMID 23990942, 2013). "In the current study, in order to investigate the potential use of NNMT as therapeutic target for human oral cancers, we employed a RNA interference technique to reduce NNMT expression in oral cancer cells and analyzed their phenotypic changes." (PMID 23990942, 2013). "In vivo tumorigenicity of oral cancer cells with stable knockdown of NNMT was assayed by using xenograft models." (PMID 23990942, 2013). "Further clarifying the interaction mechanism between Klotho and NNMT in oral cancer may provide a theoretical basis for novel targeted therapeutic strategies, thereby improving the clinical predicament of poor prognosis for oral cancer patients." (PMID 40427517, 2025). "RNA interference-directed knockdown of NNMT in cancer cells might represent a convenient and novel tool for studying the biological role of NNMT and raises the potential of its application for oral cancer therapy." (PMID 23990942, 2013). "Overall, this evidence indicates that NNMT may provide an excellent molecular target for oral cancer therapy." (PMID 23990942, 2013). "Finally, high NNMT levels were also detected in urinary samples of bladder and oral cancer patients, suggesting that its presence in biological fluids could be used as a marker for the early diagnosis of these malignancies." (PMID 34827592, 2021). "All these experimental data seem to suggest that NNMT plays a critical role in the proliferation and tumorigenic capacity of oral cancer cells, and its inhibition could represent a potential molecular approach to the treatment of oral carcinoma." (PMID 23990942, 2013). "Notably, NNMT and ENAH have been shown to enhance the proliferative and tumorigenic potential of oral cancer cells, while TNC contributes to an immune-suppressive tumor microenvironment in OSCC." (PMID 41044643, 2025). "As shown, NNMT, FLI1, SLPI, LAMP3, SERPINA1, GAS6, and CD274 have been often used as biomarkers for OSCC or head and neck cancer, while other genes listed have seldom been investigated in oral cancer and may be considered as novel biomarkers for OSCC prevalence and treatment." (PMID 28286742, 2017).
papillary thyroid cancers (7 papers, 2009 to 2021). "Recently, NNMT promoter has been cloned and studied in papillary thyroid cancer cell lines, in which it was shown to be activated by hepatocyte nuclear factor beta (HNF-1β)." (PMID 23990942, 2013). "Recently, NNMT promoter was cloned and studied in papillary thyroid cancer cell lines, where it was shown to be activated by hepatocyte nuclear factor-1β." (PMID 19216803, 2009). "Moreover, in BHP 18–21 papillary thyroid cancer cells, the histone deacetylase inhibitor depsipeptide reduced NNMT expression through HNF-1β downregulation." (PMID 23990942, 2013). "Indeed, NNMT expression may be useful in the differential diagnoses between papillary carcinomas and benign thyroid lesions with papillary architecture, or between primary or recurrent odontogenic lesion." (PMID 34827592, 2021).
prostate carcinoma (7 papers, 2014 to 2026). A carcinoma that arises from epithelial cells of the prostate gland. "We believe that future research should investigate the use of small-molecule inhibitors of NNMT as potential therapeutics for overcoming prostate cancer radiorecurrence." (PMID 40497995, 2025). "In agreement with this, through a bioinformatic analysis of TCGA, we discovered that NNMT was in greater abundance at the RNA level in prostate cancer compared to benign prostate tissue." (PMID 40497995, 2025). "NNMT was found to have a significant role in radioresistance, which has implications for future studies targeting radiorecurrent prostate cancer." (PMID 40497995, 2025). "This review aims to report and discuss evidence available in scientific literature, dealing with NNMT expression and the potential involvement in main urologic neoplasms, namely, renal, bladder and prostate cancers." (PMID 34439880, 2021). "Additionally, Zhou and colleagues reported that NNMT was up-regulated in prostate cancer specimens by immunohistochemistry, and negatively correlated with Gleason score." (PMID 40497995, 2025). "This implicates NNMT as a potential novel target for treatment of radioresistant prostate cancer." (PMID 40497995, 2025). "Interestingly, they noted that elevated NNMT expression was correlated with improved outcomes in men with advanced prostate cancer." (PMID 40497995, 2025). "It is only recently that NNMT was found to be upregulated in prostate cancer (PCa)." (PMID 34439880, 2021). "Considering the observation that NNMT expression is increased in HGPIN and well-differentiated PCa compared with BPH, we hypothesize that NNMT may exhibit different roles in the early stages of prostate cancer and during its progression toward metastatic or castrate-resistant states." (PMID 25120681, 2014).
colon cancer (6 papers, 2009 to 2024). "In human colon cancer cells, silencing NNMT resulted in approximately a 30% increase in NAD+ levels, whereas NNMT overexpression decreased NAD+ levels by 30%." (PMID 38919254, 2024). "Silencing NNMT in a human colon cancer cell line (HT-29 cells) resulted in an approximate 30% increase in the NAD+ levels, while the overexpression of NNMT in a human colon cancer cell line (SW480 cells) led to a 30% decrease in the intracellular NAD+ levels." (PMID 38921477, 2024).
hyperlipidemia (6 papers, 2016 to 2025). "Dysregulated lipid metabolism is a hallmark of hyperlipidemia, and NNMT activity strongly influences transcriptional regulators." (PMID 41008588, 2025). "Genetic evidence also supports this link: the rs1941404 single-nucleotide polymorphism (SNP) in the NNMT gene is significantly associated with hyperlipidemia in the Chinese Han population, likely through its effect on resting energy expenditure." (PMID 41008588, 2025). "A specific single-nucleotide polymorphism (SNP) located within the NNMT gene, rs1941404, was significantly linked to the occurrence of both hypertension and hyperlipidemia." (PMID 38921477, 2024). "Our prior research established a notable correlation between a specific single-nucleotide polymorphism (SNP) in the NNMT gene, rs1941404, and the incidence of hypertension and hyperlipidemia among the Chinese Han population." (PMID 38921477, 2024). "The rs694539 NNMT polymorphism is associated with non-alcoholic steatohepatitis, and rs1941404 is associated with hyperlipidemia." (PMID 32651404, 2020). "The rs1941404 variation in NNMT is significantly associated with hyperlipidemia and the CC is the risk genotype (recessive inherence mode)." (PMID 27999813, 2016). "Furthermore, our previous analysis of 19 tagSNPs in the NNMT gene sequences of Chinese Han patients revealed a significant association between the variant at rs1941404 and hyperlipidemia." (PMID 38919254, 2024). "NNMT contributes to hyperlipidemia not only through lipid metabolism but also via Hcy regulation." (PMID 41008588, 2025). "Consequently, it is plausible that NNMT’s involvement in hyperlipidemia is mediated through its impact on both sugar and fat metabolism." (PMID 38919254, 2024). "Moreover, NNMT might contribute to hyperlipidemia by influencing plasma Hcy levels." (PMID 38919254, 2024). "However, the association between rs694539 variation and hyperlipidemia has not been reported yet, and whether there are any SNPs in NNMT significantly associated with hyperlipidemia is still unclear." (PMID 27999813, 2016).
liver cancer (6 papers, 2013 to 2025). An epithelial or non-epithelial malignant neoplasm that arises from the liver. "Elevated NNMT levels have been observed in various liver cancers, and this upregulation is linked to cancer growth and progression." (PMID 40427612, 2025). "A reduction in NAD+ levels could represent a key underlying mechanism through which NNMT facilitates the progression of liver cancer, substantially elevating the risk of oncogenesis." (PMID 40427612, 2025). "The interactions of these enzymes with liver cancer are closely linked, suggesting that heightened NNMT activity could potentially influence the regulatory mechanisms of these enzymes in an indirect manner." (PMID 40427612, 2025). "Although the specific mechanisms by which NNMT influences liver cancer progression and its potential as a therapeutic target remain poorly understood, accumulating evidence suggests that NNMT plays significant roles in diagnosis, treatment, and prognosis." (PMID 40427612, 2025). "These comparisons underscore the need to dissect NNMT’s role through both pan-cancer and tissue-specific lenses, particularly in liver cancer where viral hepatitis and unique methionine cycle dependencies amplify its pro-tumorigenic effects." (PMID 40427612, 2025). "It is noteworthy that, while some studies suggest NNMT is expressed at low levels in liver cancer, others report its high expression." (PMID 40427612, 2025). "The contribution of NNMT in modulating various metabolic pathways in liver cancer cells is well-understood." (PMID 40427612, 2025). "Despite evidence indicating NNMT expression in liver cancer and its role in tumor proliferation and metastasis, the precise mechanisms underlying its influence on cancer progression remain poorly understood." (PMID 40427612, 2025). "Previous research has indicated that NNMT acts as an oncogenic in liver cancer, contributing to the invasion and metastasis." (PMID 40427612, 2025). "This subsequent section will delve into the metabolic regulatory functions of NNMT within the context of liver cancer." (PMID 40427612, 2025). "Overall, the research into NNMT’s contribution to drug resistance in liver cancer cells presents novel viewpoints and methods for treating liver cancer." (PMID 40427612, 2025). "NNMT expression is elevated in many types of malignant tumors, but in liver cancer, its expression has been found to be reduced, although abundant, when compared to adjacent, non-transformed hepatic tissue." (PMID 34073600, 2021). "Based on the present and previous findings, we surmised that NNMT promotes invasion and metastasis in liver cancer." (PMID 31294922, 2019). "Therefore, further investigation is crucial for elucidating NNMT’s role in liver cancer and advancing the development of targeted therapeutic strategies." (PMID 40427612, 2025). "Moreover, studies suggest that NNMT is a potential therapeutic target for the statin-induced inhibition of liver cancer cell metastasis." (PMID 40427612, 2025). "Overall, compared to a recently published NNMT review, this article systematically sorted out the mechanism of NNMT regulating immune escape in liver cancer through metabolic reprogramming for the first time, and proposed its potential as a target for combination therapy." (PMID 40427612, 2025). "Although many challenges remain, with ongoing research, NNMT may be established as a novel therapeutic target for liver cancer, bringing unprecedented hope to patients." (PMID 40427612, 2025). "NNMT expression and activity may influence liver cancer cell drug resistance by modulating the activity of drug-metabolizing enzymes." (PMID 40427612, 2025). "Considering that NNMT is a negative regulator of autophagy, its transient, reduced expression in liver cancer could promote cancer cells survival, under nutrient starvation, by activating autophagy." (PMID 34073600, 2021).
liver cancer (continued). "Conversely, in individuals with liver cancer, the diminished functionality of glycine N-methyltransferase (GNMT) increases the dependency on NNMT for SAM synthesis, given that GNMT is the predominant enzyme accountable for the consumption of SAM." (PMID 40427612, 2025). "This discovery highlights the pivotal function of NNMT in curbing OXPHOS, a process that liver cancer cells predominantly eschew in favor of glycolysis to fuel their proliferation and sustain their existence." (PMID 40427612, 2025). "Understanding how NNMT regulates the NAD+ biosynthesis pathway and the methionine cycle could provide new insights into liver cancer pathogenesis and treatment." (PMID 40427612, 2025). "NNMT, a key metabolic enzyme, regulates the levels of S-adenosyl-L-homocysteine (SAH), N1-methylnicotinamide (MNAM), S-adenosyl-L-methionine (SAM), and nicotinamide (NAM) in liver cancer cells." (PMID 40427612, 2025). "In liver cancer, unlike other cancers, the NNMT level is lower than in normal tissues, and in fact its downregulation has been implicated in liver cancer." (PMID 36750850, 2023). "Nevertheless, the role of NNMT in liver cancer cell invasion and metastasis has not been elucidated so far." (PMID 31294922, 2019). "NNMT promoter activity has also been correlated to the activation of signal transducer and activator of transcription 3 (STAT3) in colorectal tumor tissues and Hep G2 liver cancer cells stimulated with interleukin (IL)-6." (PMID 23990942, 2013). "In this pathological state, the disruption of the methyl donor balance, along with the dysregulation of NNMT, SAM, SAH, MNAM, and NAM, may lead to abnormalities in the regulation of NNMT’s metabolic pathways, potentially linking these changes to the pathogenesis of liver cancer." (PMID 40427612, 2025).
atherosclerosis (5 papers, 2013 to 2025). A disease characterized by the build-up of fatty material and calcium deposition in the arterial wall resulting in partial or complete occlusion of the arterial lumen. "In summary, NNMT upregulation is linked to atherosclerosis progression, vascular inflammation, plaque instability, and thrombosis." (PMID 41008588, 2025). "Experimental studies using small-molecule NNMT inhibitors and RNA interference have shown promising cardiometabolic benefits in preclinical models, including improved insulin sensitivity, reduced atherosclerosis, and attenuated cardiac dysfunction." (PMID 41008588, 2025). "Atherosclerosis, nonalcoholic fatty liver disease, cancer, and dementia are only a few of the contexts in which a downregulation or absence of NNMT can visibly impact the cellular phenotype in a physiologically significant manner." (PMID 37889548, 2023). "Among non-neoplastic diseases, an overexpression of NNMT was also detected in atherosclerosis, chronic obstructive pulmonary disease (COPD), and Parkinson's disease." (PMID 23990942, 2013).
esophageal cancer (5 papers, 2021 to 2023). A primary or metastatic malignant neoplasm involving the esophagus. "NNMT expression was significantly associated with the TNM stage in adrenocortical carcinoma (ACC), BLCA, BRCA, esophageal carcinoma (ESCA), KIRC, ovarian serous cystadenocarcinoma (OV), STAD, testicular germ cell tumors (TGCT), and THCA." (PMID 36817086, 2023). "LGG, HNSC, GBM, STAD, SKCM, PRAD, esophageal carcinoma (ESCA), and UVM were selected to demonstrate the association between immune infiltration and NNMT expression." (PMID 36386816, 2022).
lymph node metastasis (5 papers, 2014 to 2023). "Previous studies reported the high expression of NNMT in OSCC patients was negatively associated with lymph node metastasis." (PMID 36291696, 2022). "The association between NNMT expression and the clinicopathological factors of PCa, including patient age, serum PSA level, tumor stage, Gleason score, distant metastasis and lymph node metastasis, was investigated." (PMID 25120681, 2014). "Then, we found that high expression of NNMT both in tumor cell and stroma are associated with advanced TNM stage, lymph node metastasis and distant metastasis, as well as poor OS, which indicated NNMT may play a vital role in metastasis of CRC." (PMID 34539890, 2021).